BMI1 (BMI1 proto-oncogene, polycomb ring finger)
Diseases named in the same sentence as BMI1 in open-access papers (continued):
Sharing a sentence is not in itself a finding about the gene and the disease.
tumor (continued). "DNMT3A knockdown prevented VEGFA‐driven miR‐128‐2 loss, and the increase in Bmi1 and tumor spheres." (PMID 28179359, 2017). "BMI1 is thought to play an important role in maintaining self-renewal of stem cell populations and it may function in tumorigenesis by repressing tumor suppressor genes through its associated ubiquitin E3 ligase activity." (PMID 29163782, 2017). "Moreover, the reduction of BMI-1 protein levels was associated with apoptosis in tumor cells and increased susceptibility to cytotoxic agents and radiation therapy." (PMID 26887044, 2016). "Notably, compared with the other combinations, the co-expression of CD133 and BMI-1 proteins was significantly associated with tumor AJCC stages, T stage and the lymphatic metastasis." (PMID 26840020, 2016). "For example, abnormal activation of many normal stem cell regulators, including Notch, Hedgehog, Wnt/β-catenin, c-Myc, and Bmi-1, which promote self-renewal in various stem cells and cause neoplasia when deregulated, have been identified in the context of CSCs." (PMID 25938540, 2015). "High expression of BMI1 was associated with aggressive tumor behavior and poor outcome." (PMID 23820733, 2013). "Our findings suggest that TAMs may cause increased Bmi1 expression through miR-30e* suppression, leading to tumor progression." (PMID 24312366, 2013). "Additional work has revealed that BMI1 had been associated with tumor development and progression." (PMID 22539939, 2012). "The strong association of BMI1 overexpression and luminal A type tumours may therefore suggest that BMI1 is selectively oncogenic in ER-positive cells, where it can over-rule their arrested state." (PMID 19099573, 2008). "Because BMI1 suppresses growth arrest mediated by the Rb pathway and the early growth arrest of HMECs has been linked to p16CDKN2A expression, BMI1 expression is a potential escape mechanism for growth-arrested ERα-positive tumour cells." (PMID 17573968, 2007). "In addition to the tumor spheroid phenotype observed upon inhibiting the VM phenotype, we observed alterations in glycosylation of integrin β1, loss of VE‐cadherin and a decrease in stem cell marker Bmi‐1." (PMID 34320274, 2021). "Here, we took advantage of in vitro generated ADMs and isolated tumor cells, which show, similarly to in vivo models, a loss of acinar differentiation gene expression as well as elevated levels of the transcriptional repressors Bmi1 and Ring1b and their catalyzed histone modification H2AK119ub." (PMID 26716510, 2016). "More importantly, we demonstrated that silencing BMI1 expression in two independent pGBM models not only led to significant suppression of cell proliferation and neurosphere formation in vitro, but also caused the abrogation of xenograft tumor formation in vivo in mouse brains." (PMID 25526772, 2014). "Furthermore, as we have shown that Bmi1 regulates hepatic oval cell expansion via regulating the Ink4A/Arf locus, it would be important to determine whether loss of Ink4A/Arf locus can rescue the tumor phenotype in Bmi1 null mice." (PMID 23029524, 2012). "Notably, BMI-1 is associated with both humoral and T-cell responses, suggesting that it represents a novel family of tumor-associated antigens (TAAs) that might be potential target for immunotherapy." (PMID 22132147, 2011). "We previously demonstrated that exogenous BMI1 overexpression in basal epithelial SCs enhanced tumor formation upon 4-NQO treatment in our OSCC mouse model." (PMID 41385756, 2026). "Our findings reveal that tumor-stroma crosstalk via the CXCL12/CXCR4/BMI1 axis plays a central role in sustaining miCSC-driven metastasis and therapy resistance in PDAC." (PMID 41991735, 2026).
tumor (continued). "Surprisingly, in cultured GBM tumor cells, Bmi‐1 mRNA expression was significantly higher in CD133‐negative than in CD133‐positive cells." (PMID 39791545, 2025). "It has been noted that miR-200b is partially silenced through DNA methylation, which allows it to inhibit tumor growth and invasion by directly targeting BMI1 and ZEB1 in HCC." (PMID 39829957, 2025). "It was found that miR-200 directly targets BMI1 and suppresses tumor development by promoting apoptosis." (PMID 40469123, 2025). "results is 185, whereas the sum of the number samples (N) for the Bmi1 levels for the Tumor Size results is 180 samples." (PMID 41187110, 2025). "In this study, we demonstrate that Dioscin targets the BMI1-Noxa axis and facilitates BMI1 degradation by ubiquitination to exert its anti-tumor activity." (PMID 39744574, 2025). "SOX9 also promotes uncontrolled proliferation and malignant properties in tumor cells by inhibiting INK4A/ARF expression through BMI-1 induction." (PMID 39907598, 2025). "In GBM, Bmi‐1's aberrant expression level explains the activation of self‐renewal pathways upon interacting with multiple tumor suppressor pathways to preserve GSCs undifferentiated state." (PMID 39791545, 2025). "Specifically, PIWIL4, SATB1, GSE1, NCOR1, SAP30L, ATM, and BMI1 were significantly downregulated in tumor tissues relative to normal controls, while BUB1, CHEK1, MASTL, DNAJC2, UBE2D1, and SSRP1 showed pronounced upregulation." (PMID 41208974, 2025). "It is widely believed that the INK4a/ARF tumor suppressor locus is a critical downstream target of Bmi‐1." (PMID 39791545, 2025). "Furthermore, pharmacological or genetic inhibition of BMI1 not only aids in eliminating BMI1+CSCs but also potentiates the effects of PD-1 blockade by activating the intrinsic immunity of tumor cells, thereby suppressing metastatic tumor growth and reducing the risk of tumor recurrence." (PMID 41368628, 2025). "It is worth noting that although Bmi‐1 induces significant proliferation and self‐renewal by remodeling the tumor cells surrounding the microenvironment, Bmi‐1 is incapable alone of promoting tumor formation without another mutation." (PMID 39791545, 2025). "Subsequently, Bmi‐1 inhibits the expression of tumor suppressors, contributes to tumor malignancy, and facilitates the evasion of senescence in GSCs." (PMID 39791545, 2025). "Tumor formation occurs in vivo when p16Ink4a and p19Arf expression are decreased due to upregulation of Bmi-1." (PMID 39866230, 2025). "One plausible explanation is Bmi‐1's involvement in suppressing apoptotic‐related genes in tumor cells, thus contributing to the evasion of senescence and maintenance of cell proliferation." (PMID 39791545, 2025). "In NPC tissue sections, the nuclear BMI1 intensity in tumor cells varied between low intensity (score of 0 or 1) to high intensity (score of 2 or 3) (white arrows)." (PMID 40647395, 2025). "BMI1 is considered to be a key factor in regulating tumor metastasis and recurrence, and its abnormal upregulation can effectively aggravate the epithelial-mesenchymal transition, resistance formation, and thrombi formation." (PMID 40087716, 2025). "Similar to AY-Sall4 KOhepΔ, tumor-specific Bmi1 ablation significantly impaired AY-CCA formation, as assessed by prominently reduced gross CCA formation and LW/BW ratio." (PMID 40932240, 2025). "These cells, marked by proteins such as prominin-1 (CD133), SRY-box transcription factor 2 (SOX2), and polycomb complex protein BMI-1 (BMI-1), contribute to therapy resistance and tumor recurrence." (PMID 40722337, 2025). "In the context of ARMS, BMI1 expression is consistently elevated across tumor samples, including patient-derived xenografts and various cell line models." (PMID 40508013, 2025). "Our comprehensive review also provides an explanation of the mechanistic basis of Bmi‐1‐mediated epigenetic changes that promote the stemness state of tumor cells and it proposes Bmi‐1 as a possible prognostic biomarker of GBM." (PMID 39791545, 2025).
tumor (continued). "Here, a berberine derivative B68 is developed, which specifically induces tumor cell senescence by targeting BMI1." (PMID 39721027, 2025). "As a result, Bmi‐1 activates both anti‐apoptotic pathways at the transcriptional (repression of tumor suppressor genes) and non‐transcriptional levels (activation of DNA repair machinery)." (PMID 39791545, 2025). "We delivered SB-Cas9-sgBmi1 plasmid, along with AY, into FVB WT mice via HDTVI (Bmi1 KOCCAΔ) and evaluated tumor development at 6 to 8 weeks after injection." (PMID 40932240, 2025). "We find that Bmi‐1 participates in regulating the gene expression and chromatin structure of several tumor suppressor genes or cell cycle inhibitors." (PMID 39791545, 2025). "FOXA1 acts as a tumor suppressor, and its loss promotes NPC progression and cisplatin resistance, partially through BMI1-mediated mechanisms." (PMID 40623983, 2025). "In GBM, Bmi‐1 enhances self‐renewal and proliferation by repressing tumor suppressor genes and cell cycle inhibitors, such as p16, p19, and p21, to promote tumor cell undifferentiation." (PMID 39791545, 2025). "Considering the importance of BMI1 for CLL transformation derived from our tumor trajectory experiments, it is a confirmatory result that, in our tumor driver screening, again, BMI1 was highlighted as an important player in tumor progression." (PMID 40938978, 2025). "Mechanistically, BMI1 drives tumor aggressiveness by transcriptionally repressing PTEN, thereby activating the PI3K/Akt pathway, which induces EMT and promotes metastatic dissemination." (PMID 40623983, 2025). "Combination of PTC209@VNP-HA plus cisplatin significantly inhibited tumor volume and weight growth compared to the cisplatin alone, suggesting that BMI1 inhibition overcomes cisplatin resistance in HNSCC in vivo." (PMID 40242481, 2025). "The corresponding author stated that the total number of samples analyses was 185, but only 180 samples had both protein level values for Bmi1 and tumor size results available for analysis." (PMID 41187110, 2025). "By enhancing H3K27me3 at the EfnA5 promoter locus, Bmi‐1 regulates and reinforces EfnA5 repression to promote proliferation, invasion, and tumor formation in GIC in both mouse and human models." (PMID 39791545, 2025). "Then, we studied the role of SOX4-induced BMI1 expression in tumor proliferation and metastasis by establishing subcutaneous and orthotopic models in mice." (PMID 39349443, 2024). "Focal nuclear immunostaining for BMI-1 was also observed mostly in both regions of primary tumours, with positive tumours detected only in a few and scratched metastatic tumour cells." (PMID 38719848, 2024). "Bmi-1 is expressed in various tumors and is closely related to tumor occurrence, development and prognosis." (PMID 38914697, 2024). "Studies have shown that E2A-PBX1 upregulates the expression of BMI-1, while Bmi-1-deficient hematopoietic progenitor cells show resistance to E2A-PBX1-induced tumor metaplasia." (PMID 39129784, 2024). "Bmi-1 expression was low in tumor tissues transfected with siRNA-Bmi-1 and in tumor tissues co-transfected with siRNA-Bmi-1 and RKIP." (PMID 38914697, 2024). "Having shown that anti-BMI-1 molecules affect in culture cell cycle progression, we next tested their effect on in vivo tumor growth, by generating xenograft models of H1975 in immunocompromised NSG mice." (PMID 38546390, 2024). "Ki67 expression in tumors was determined by immunohistochemistry, and the proportion of Ki67-positive cells in tumors was decreased in tumor-bearing mice established by OCSCC cells with BMI1 or ITGB1 knockdown." (PMID 38254031, 2024). "We observed an increase in ALDH1+/CD44+/BMI-1- tumour cells in metastatic lesions compared to primary tumours." (PMID 38719848, 2024).
tumor (continued). "We then examined the impact of Bmi-1 silencing on NPC cell growth in vivo by performing tumor xenograft experiments." (PMID 37219449, 2023). "On the other hand, we did find positive correlations between Bmi-1 levels and the tumor size (‘T’; P = 0.030), lymph node invasion (‘N’; P < 0.001) and clinical stage (III-IV vs. I-II; P = 0.001) of NPC." (PMID 37219449, 2023). "Tumor cells as well as a plethora of stromal cells from the tumor microenvironment express Bmi-1, which highly clouds the prognostic value of this marker." (PMID 36726797, 2023). "Here, we develop spontaneous preclinical HCC animal models with BDTT to identify the role of BMI1 expressing tumor initiating cells (BMI1high TICs) in inducing BDTT." (PMID 37923799, 2023). "Clinically, the tumor expression between miR-218-1-3p and BMI1/CTSB is negatively correlated in HCC patients." (PMID 37923799, 2023). "Various highly selective small molecules (e.g., PTC-028, PTC-209 and PTC596) have been developed to inhibit Bmi-1 for basic and clinical tumor treatment, and the results have been encouraging." (PMID 37219449, 2023). "Bmi-1 expression is upregulated in CSCs, which is augmented by tumor-promoting factors and various conventional chemotherapies." (PMID 36726797, 2023). "In conclusion, our study revealed that Bmi-1 downregulation suppressed tumor progression during the pathogenesis of NPC." (PMID 37219449, 2023). "BMI1, on the other hand, as a member of the polycomb group (PcG) proteins, acts as an epigenetic silencer of tumor suppressor genes and is involved in tumor proliferation, progression and chemoresistance." (PMID 36980635, 2023). "We next assessed stemness marker expression and tumor sphere formation to determine the effects of Bmi-1 inhibition on NPC stem cell-like populations." (PMID 37219449, 2023). "Our analysis indicated a positive correlation between the expression of the TIC-related protein signature and BMI1 in the tumor regions." (PMID 37923799, 2023). "mPEG-CC-cRGD/Bmi-1RNAi-PTX targeted tumor tissues in vivo in mice, down-regulated the expression of Bmi-1 and made tumor cells to be more sensitive to PTX." (PMID 38095348, 2023). "Restoring the normal levels of the brain-specific miR-128 within GBM has indicated tumor suppressive effects mediated through an interaction with the E3F3a and BMI1 genes and reducing the levels of proliferation and invasiveness." (PMID 36649032, 2023). "Bmi-1+ tumor cells formed significantly more spheres and tumors than Bmi-1− cells, providing strong evidence for the direct role of Bmi-1 in tumorigenesis both in vitro and in vivo." (PMID 36726797, 2023). "Downregulation of Bmi-1 resulted in an increase in p16Ink4a and p19Arf expression leading to senescence, while upregulation of Bmi-1 resulted in a decrease in p16Ink4a and p19Arf expression leading to tumor formation in vivo." (PMID 36726797, 2023). "DAB pixel density indicates a substantial increase in BMI1 expression in the 56Fe-irradiated tumor (four-fold, p < 0.01) and normal intestine (two-fold, p = 0.012) relative to the spontaneous or unirradiated normal mucosa, respectively." (PMID 37686516, 2023). "For example, Bmi-1 promotes tumor proliferation, metastasis and drug resistance by activating NF-κB signaling pathway." (PMID 35897796, 2022).
tumor (continued). "Due to the direct interaction between SOX2/NANOG/BMI1/KLF4 in the invasiveness of tumor cells, as well as its biological significance in the progression of ESCC, SOX2 expression can enhance malignancy by inducing stemness properties and EMT in ESCC." (PMID 36553636, 2022). "Lineage tracing analysis upon the induction of chemical carcinogenesis with 4NQO on oral epithelial cells and development of SCCs identified some tumor cells also expressed BMI1." (PMID 35159370, 2022). "Direct inhibition of Bmi-1 abrogates head and neck cancer stem-cell self-renewal and increases tumor sensitivity to cisplatin." (PMID 35897796, 2022). "According to Ilango Balakrishnan, inhibiting BMI1 reduces cell self-renewal and slows tumor growth via the induction of senescence." (PMID 35566032, 2022). "Accordingly, targeting BMI1 with BI‐44 suppressed LAC tumour formation and progression in pre‐clinical model." (PMID 35794816, 2022). "Although A549 contain wild‐type EGFR, knockdown of BMI1 still blocked spheroid and tumour formations." (PMID 35794816, 2022). "As a result, the inhibition of BMI1 increases tumor infiltration of CD8+ T cells, improves the efficacy of ICB therapy, and prevents tumor metastasis and relapse in a HNSCC mouse model." (PMID 35455671, 2022). "Accordingly, BMI1 significantly fostered in vivo tumor growth, as well as the number of Ki67 positive cells in vivo." (PMID 35205666, 2022). "Ulteriore analysis showed that BMI1 expression was significantly lessened in tumor tissues formed from PTC-209 treated cells." (PMID 35346195, 2022). "These combined results suggest that BMI1‐mediated oncogenesis can be variable in different types of tumour." (PMID 35794816, 2022). "Some studies have found that in NSCLC, the level of BMI1 expression is closely related to patient survival and tumor size." (PMID 36499676, 2022). "It has been reported that miR-29a can regulate the expression of the BMI1 gene through NF-κB and Wnt/β-catenin signaling pathways, thereby inhibiting the growth, migration, and invasion function of tumor cells." (PMID 35113040, 2022). "The tumours from each of these conditions were paraffin embedded and immunohistochemistry (IHC) was performed for two stemness markers, Oct4 and Bmi1." (PMID 35195687, 2022). "Downregulation of EZH2 decreases the levels of H3K27me3, displaces BMI1, and activates p16Ink4a transcription, which promotes the tumor cell senescence." (PMID 35409271, 2022). "Mechanistically, knockdown of Bmi-1 not only eliminated CSCs, but also sensitized tumor cells to anti-PD-1 antibodies by recruiting CD8+ T cells." (PMID 35897796, 2022). "The activation of the WNT pathway and the inhibition of tumor suppressor genes (TSGs) through BMI1 can facilitate tumor invasion and progression." (PMID 36553636, 2022). "In conclusion, we summarize the role of Bmi-1 in tumor progression, reveal the pathophysiological process and molecular mechanism of Bmi-1 in tumors, and provide useful information for tumor diagnosis, treatment, and prognosis." (PMID 35897796, 2022). "These combined results suggest that LAC tumour can be reliant on BMI1 to sustain the survival and progression in vivo, and targeting BMI1 is a promising approach for LAC treatment." (PMID 35794816, 2022). "Overexpression of mutant EGFR in BEAS‐2B (a non‐tumour human lung epithelial cell line) also induced BMI1 expression." (PMID 35794816, 2022). "Semiquantitative intensity analysis of the IHC sections showed a significant reduction in Oct4 and Bmi1 expression in the combinatorial treatment, and doxorubicin alone enriched for stemness markers after eliminating the bulk tumour cells." (PMID 35195687, 2022). "In mouse model, when LAC cells were subcutaneously implanted in nude mice, knockdown of BMI1 resulted in defective tumour formation in three cell lines tested." (PMID 35794816, 2022).